BAX (BCL2 associated X, apoptosis regulator)
Diseases named in the same sentence as BAX in open-access papers (continued):
Sharing a sentence is not in itself a finding about the gene and the disease.
tumor (continued). "Loss of BAX by RNA interference in CSCC enhanced the tumor proliferation, migration, invasiveness, and resistance against apoptosis." (PMID 28556798, 2017). "Loss of BAX by highly-expressed miR-365 enhanced the CSCC tumor resistance against tumor-suppressive apoptosis." (PMID 28556798, 2017). "Tumor size and mass were evidently larger at the end of the evaluation while the loss of BAX expression in the siBAX group was also confirmed by qPCR, Western blot, and IHC staining." (PMID 28556798, 2017). "The expression of the differentiation marker, sucrase isomaltase (SI) and the pro-apoptotic marker, Bcl-2 associated X protein (BAX) were significantly down-regulated in the tumor samples compared with the adjacent mucosa (n = 54, p < 0.001)." (PMID 25701758, 2015). "Quantitative analysis of mRNA levels in these tumor tissues revealed that the Pro allele is associated with significantly reduced levels of p21 and BAX expression." (PMID 23071787, 2012). "Nonetheless, it is unlikely that chemotherapy use substantially differed according to TGFBR2 or BAX mutation status in tumor, since such data were typically unavailable for treatment decision making." (PMID 21949851, 2011). "Our findings suggest that TGFβRII, BAX, hMSH3 and hMSH6 frameshift mutations are relatively later stage events in tumor progression for sporadic CRC with MSI." (PMID 20565851, 2010). "Therefore, in this study, we examined circ-BAX-18 expression in BrCa tissues and its potential association with tumor features and patients' prognosis." (PMID 42196148, 2026). "Concurrently, BAX-mediated mitochondrial dysfunction may lead to release of damage-associated molecular patterns (DAMPs), which reprogram immune cells—particularly tumor-associated macrophages and Tregs—toward immunosuppressive phenotypes." (PMID 40382614, 2025). "Furthermore, correlation analysis of BAX expression and tumor-associated pathways was performed in macrophages to verify the mechanism of BAX upregulation in UCEC macrophages." (PMID 39744500, 2025). "It is noteworthy that systemic targeting of BAK or BAX may interfere with physiological apoptosis in normal cells, such as those in the hematopoietic and nervous systems, thereby increasing tumor risk and disrupting immune homeostasis." (PMID 41514922, 2025). "This not only impaired tumor cell proliferation under hypoxic conditions but may also increase their susceptibility to apoptosis by reducing the activation of BAX and BAD proteins." (PMID 39031012, 2024). "It was suggested that BAX frameshift mutations play a key role in the process of tumor progression." (PMID 33182707, 2020). "Our results demonstrate that predisposition to BAX activation impairs tumor biology in HCC." (PMID 32486514, 2020). "BAX itself has been found mutated with loss of function in several cell lines of human hematopoietic malignancies, indicating that this pro-apoptotic protein can function as a tumor suppressor in these diseases." (PMID 27494852, 2016). "BAX expression is also associated with tumor development and hematological malignancies." (PMID 23777485, 2013).
tumor (continued). "Furthermore, our results demonstrate that BAX mRNA expression is significantly associated with various clinicopathological parameters, including primary tumor extent, regional lymph node status, and presence of distant metastases." (PMID 23777485, 2013). "Mutations in BAX have been shown to mediate tumor progression in later stages of CRC with MSI." (PMID 23209772, 2012). "Only serum levels of C20 CER, C22 CERand C24 CER were found to positively correlate withthe BAX/BCL2 ratio in tumour tissues in patientsbefore undergoing nCRT." (PMID 40821650, 2025). "Mechanistically, RSV downregulates β-catenin and Oct4 while activating pro-apoptotic BAX in CSCs, with hydrogel-mediated delivery enhancing tumor penetration by 40% compared to free RSV." (PMID 40690143, 2025). "When the 1097 tumor samples were compared with 114 normal tissue samples, it was shown that BAX gene had enhanced expression profile while BCL2 had lower median in tumor tissues." (PMID 41154846, 2025). "Crucially, it was found that BAX gene, as the core effector molecule in the regulation of ammonia-related cell death, has the dual value of tumor promoting biomarker and therapeutic target." (PMID 40382614, 2025). "When tested in in vivo studies, the combination of CBD (5 mg/kg) and DOX reduced tumor volume (p < 0.001, n = 4), increased the expression of BAX and cleaved caspase-3, and decreased Bcl2 and mTOR." (PMID 40006844, 2025). "The results demonstrated notable upregulation of BAX in both the DOX + tumor group and the DOX + AAV9-CDC20 + tumor groups compared with the tumor group." (PMID 40045239, 2025). "In CRC, the Bcl-2/BAX ratio has been identified as a crucial prognostic marker, correlating with tumor grade, stage, and size in patients." (PMID 41441038, 2025). "To further validate tumor cell apoptosis, we performed western blot analyses showing upregulated cleaved caspase‐3 and BAX expression with concurrent BCL‐2 downregulation in treated spheroids." (PMID 40847445, 2025). "Functional experiments further confirmed that BAX gene silencing can significantly inhibit the proliferation, clonal formation, migration and invasion of tumor cells in vitro." (PMID 40382614, 2025). "177Lu-PNP radiopharmaceuticaltherapy induced higherexpression of γH2AX, indicating that potent DNA damage occurred,and provoked the apoptotic pathways in the tumor, as evidenced bythe elevated BAX/BCL-2 ratio." (PMID 40442102, 2025). "Thymol (75 and 150 mg/kg) reduced tumor volume, induced cell death, and modulated BAX/Bcl‐2 and Wnt/β‐catenin pathways in an in vivo analysis." (PMID 40964147, 2025). "Initially, FOXP2 functions as a tumor suppressor, targeting various tumor inhibitors such as BAX, PTEN, and p16." (PMID 40003882, 2025). "Apoptosis plays a central role in the anti‐tumour response, with key regulators such as BAX, BCL‐2, and Cleaved caspase‐3 often being evaluated in mitochondrial apoptosis way." (PMID 40804775, 2025). "The expression of the antiapoptotic protein BCL2 and proinvasion-related proteins Snail and N-CAD was upregulated in 22RV1 and PC-3 tumor cells, while those of the proapoptotic protein BAX and invasion-related protein E-CAD were downregulated." (PMID 40548257, 2025).
tumor (continued). "M2 macrophages led to the overexpression of numerous genes linked to tumor growth, angiogenesis, invasion, and immune suppression in NSCLC cells, increasing the BCL2/BAX ratio and promoting cellular resistance to apoptosis." (PMID 40076874, 2025). "It has been shown that Tregs cultured with tumor cell medium exhibit reduced expression of BAX, BAK, and BIN genes, responsible for apoptosis." (PMID 39378431, 2025). "Together, these findings establish ARGs, particularly BAX, as a key molecular determinant of tumor progression and poor prognosis in ccRCC." (PMID 40382614, 2025). "BAX was a key ammonia-related gene closely related to tumor progression, and its knockdown obviously inhibit proliferation, migration and invasion of ccRCC cells." (PMID 40382614, 2025). "An overexpression of NOTCH1 in the tumour microenvironment inactivates Bcl-2-associated X protein (BAX) and Bcl-2-associated Death promoter (BAD) proteins, which help tumour cells survive and prevent immune cells from killing them." (PMID 40672020, 2025). "Accordingly, mitochondrial outer membrane permeabilisation assay using live mitochondria from RASAL2-high/chemoresistant tumour cells demonstrated attenuated release of death signal, cytochrome c, when exposed to pro-apoptotic factors BAX and tBID." (PMID 39890967, 2025). "The expression of pro-apoptotic BAX (BCL2 associated X, apoptosis regulator) and anti-apoptotic BCL2 (BCL2 apoptosis regulator) was analysed in tumour and corresponding healthy tissue samples of patients by quantitative real-time PCR." (PMID 40821650, 2025). "Single-cell analysis confirmed the activation of ammonia-related signaling pathways in the tumor microenvironment, in particular revealing specific interactions between BAX-positive tumor cells and immunosuppressive cell populations." (PMID 40382614, 2025). "This selective effect was associated with BAX and caspase-3 upregulation, BCL-2 downregulation, and apoptotic morphological changes detected exclusively in tumor cells." (PMID 41300439, 2025). "We also found the highest expression of BAX in LGG through tumor grading data in the TISIDB resource library." (PMID 39074253, 2024). "The reduced BAX/Bcl‐2 ratio in SuHx cells also appears to be driven primarily by increased Bcl‐2 expression, a finding consistent with various tumor cells, where Bcl‐2 expression is enhanced, leading to apoptosis resistance." (PMID 39175041, 2024). "In CRC cells, PGC-1α induced mitochondrial death through the BAX signaling pathway, thereby promoting apoptosis and inhibiting tumor growth." (PMID 39763669, 2024). "This leads to increased expression of the pro-apoptotic protein BAX and inhibition of the anti-apoptotic protein Bcl-2, ultimately inducing tumor cell apoptosis." (PMID 38383702, 2024). "We also evaluated the differential expression of BAX in patients with different tumor types of different ages, races and genders." (PMID 39074253, 2024). "To further validate these findings, we conducted qPCR analysis to assess the expression of ESR1, BRCA1, CTNNB1, and BAX in tumor tissue." (PMID 39045563, 2024). "In conclusion, our study demonstrated that RNA-seq and microarrays showed similar performance in predicting clinical endpoints, except for a few genes such as PIK3CA and BAX in certain tumor types." (PMID 38463169, 2024).
tumor (continued). "In contrast, PQBP1 depletion or splice‐switching antisense oligonucleotides promote exon 2 inclusion and thus increase BAX expression, leading to inhibition of tumor growth." (PMID 38342602, 2024). "BAX was the only gene with ‘decreased’ invasive tumor properties but positively correlated with KDM7A-DT." (PMID 38756663, 2024). "Deeper staining indicated that BAX expression was higher in tumor tissues than in normal tissues at the protein level." (PMID 39074253, 2024). "In vitro and in vivo study on MDA‐MB‐231 cells demonstrated that cannabidiol with doxorubicin can increase the expression of proteins involved in apoptosis like caspase‐3 and BAX; furthermore tumor size was significantly decreased as observed in this study." (PMID 39503169, 2024). "IHC staining of tumor tissues showed increased Ki67 and Bcl2 expression and decreased BAX expression in the overexpression group, while the opposite trends were observed in the knockdown group." (PMID 39030638, 2024). "The rest of the cells at the primary tumor site acquired several unique mutations (in genes SRC, SALL4, BAX, SMAD3), but with a slower mutation rate (PT2 PT3, PT5)." (PMID 38685065, 2024). "Altogether, it implies that apoptosis of human PDAC xenograft tumor was involved with the upregulation of BAX protein compared to the NC group." (PMID 38499634, 2024). "It binds to the BH3 domain of BCL2 with subsequent release of sequestered BH-3-only proteins, thereby triggering BAX/BAK-mediated rapid tumor-cell death and anti-tumor activity." (PMID 38421404, 2024). "Compared with the control group, the tumor tissue is necrotic, the blood vessels in the tumor are atrophied, the protein expressions of BAX and Cleaved-Caspase-3 in the tumor are increased, and the protein expressions of Bcl-2 and Bcl-xL are decreased." (PMID 38633608, 2024). "Activin A suppression increased the accumulation of α‐SMAhigh/PRRX1low CAFs and led to the infiltration of CD3‐ or CD8‐positive T cells with a concomitant increase of BAX expression in PDAC tumor cells." (PMID 37083240, 2023). "We measured the levels of BAX and Bcl-2 in tumor tissues to further characterize the mechanism of the gut microbiota-related anti-CRC effects of our probiotic powder." (PMID 36913356, 2023). "The results showed that BCL2, APC, TCF, WNT, AXIN, and CTNNB1 (p < 0.05) were significantly higher expressed in tumor tissues compared to adjacent healthy tissues, and BAX was higher in control tissues than tumor tissues (p < 0.05)." (PMID 37644520, 2023). "The expression of the anti-apoptotic BCL-2 gene in the CIMV-TRAIL group remained unchanged, while the mRNA level of the pro-apoptotic BAX gene was increased by 1.4 times, which indicated apoptosis activation in the tumor tissue." (PMID 36661524, 2023). "In conclusion, irisin has an apoptotic effect on PC-3, possibly through altering αVβ5 and the Bcl2/BAX and P13k-Akt signaling pathway, inhibiting tumor growth in vivo." (PMID 37568817, 2023). "As CCAT 1 contains MRE that captures miR-181a-5p, it plays a tumor promoter role by binding to miR-181a-5p and abating the effect of miR-181a-5p on its own target pro-apoptotic protein BAX in CRC cells." (PMID 37025163, 2023). "After tumor-bearing mice were treated with FA of different concentrations, the level of BAX, a positive correlation protein with apoptosis, was significantly increased, and the Oxaliplatin (L-OHP) was more obvious." (PMID 37630266, 2023). "While the mRNA level of the proapoptotic BAX protein gene was increased by 3.3 times (n = 3, **** p < 0.0001) in the tumor cells after cultivation with CIMVs-TRAIL, which indicates activation of the apoptotic pathway and stimulation of cell death." (PMID 36661524, 2023).
tumor (continued). "In this study, expression levels of BAX, Caspase-3, Caspase-9, and cleaved Caspase-3 in the blood and tumor tissues of BGC-823-bearing nude mice were increased, while Bcl-2 expression was relatively low." (PMID 36438804, 2022). "HA-PEG-nHA-ZOL NP-induced upregulation of BAX, Bcl-2, and caspase 3 destroyed the tumor metabolism balance and triggered the tumor apoptosis." (PMID 35694235, 2022). "In non-treated HCC-bearing rats, apart from the pericentral area, the staining of BAX was less intense and found at the peripheral part of the tumor nodule." (PMID 36313224, 2022). "The Bcl2 protein binds to proapoptotic members, such as BAX, a protein that induces cell death in tumor cells, to prevent pore formation and cytochrome c release." (PMID 35070357, 2022). "As a result, it leads to epigenetic silencing of gene expressions and subsequently, the inactivation of the relevant gene (i.e., MLH1) followed by mutation of tumor suppression genes encoding tumor-suppression proteins (i.e., TGFBR2 and BAX)." (PMID 35883434, 2022). "Except for E. brandianum, all extracts induced cellular autophagy in tumor cells with similar levels to that of rapamycin; but, only E. brandianum induced cellular apoptosis, likely through Bcl2 and BAX protein expressions." (PMID 35070357, 2022). "BCL-2 can prevent hepatocellular carcinoma cells from apoptosis and promote tumor formation mainly by blocking the Fas/FasL apoptosis pathway and forming a complex with BAX." (PMID 36313628, 2022). "Deficiency of 14-3-3ζ upregulated BAD and BIM and decreased MCL-1 to increase BAX, cleaved caspase 7, and cleaved caspase 3 toward tumor cell anoikis." (PMID 36230714, 2022). "The miR‐29 family primarily promotes the tissue invasion and metastasis of tumor cells while targeting BAX to prevent apoptosis." (PMID 34856073, 2022). "ILP-2 can protect cells from BAX-induced endogenous apoptosis, help tumor cells escape apoptosis, and antagonize clinical chemotherapy." (PMID 35814477, 2022). "Intriguingly, BAX expression in tumor tissues of the highest CHE dosage group (ESC + CHE 321 mg/kg) was significantly increased (P < 0.01) compared with the DOX treatment (ESC + DOX) group." (PMID 35881165, 2022). "Four tumor apoptosis-related proteins and genes, Cleaved Caspases, BAX, Bcl-2, and VEGF, were detected by immunohistochemical staining, western blotting, and RT-PCR." (PMID 35597811, 2022). "Together, the data suggest that the cytotoxicity of α-mangostin involves the activation of MOAP-1 tumor suppressor and its interaction with act-BAX, leading to mitochondria dysfunction and cell death." (PMID 35082905, 2022). "One potential function of this pathway is to link death receptors with BAX conformational change to promote tumor suppression." (PMID 35269511, 2022). "In vivo experiments were also conducted to verify that miR-126-5p promoted tumor formation and growth via immunohistochemical detection of cell infiltration and proliferation to generate markers Ki-67, BAX, and VEGF." (PMID 35056756, 2022).